EPO (erythropoietin)
Diseases named in the same sentence as EPO in open-access papers (continued):
Sharing a sentence is not in itself a finding about the gene and the disease.
polycythemia (continued). "Even before serum EPO level was included as a WHO diagnostic criterion, it was commonly believed that a raised EPO level suggested secondary erythrocytosis and excluded PV." (PMID 39421127, 2024). "This case demonstrates that secondary polycythemia can occur in children even with low EPO level, emphasizing the need to consider renal pathologies in pediatric patients with polycythemia." (PMID 39767963, 2024). "Initial investigations revealed a relatively low erythropoietin level, which prompted us to consider primary polycythemia as a potential diagnosis." (PMID 39767963, 2024). "Here, we present a 17-year-old girl with progressive polycythemia and low EPO levels, which were thought to be related to her severe left hydronephrosis." (PMID 39767963, 2024). "Lenvatinib, as a type of TKI and one of the most potent inhibitors of VEGFR, can synergistically promote the production of EPO in hepatocellular carcinoma cells under hypoxic conditions, leading to the occurrence of polycythemia." (PMID 38524578, 2024). "EPO excess results in polycythemia and suppresses liver hepcidin expression, leading to increased dietary iron absorption with the majority of excess iron consumed by erythropoiesis." (PMID 38652538, 2024). "Secondary polycythemia presents with elevated EPO levels except when secondary to autologous transfusions or the use of performance-enhancing anabolic steroids." (PMID 39280364, 2024). "Neurologic and liver disease are attributed to Mn toxicity, while polycythemia is attributed to EPO excess." (PMID 38652538, 2024). "The proposed mechanism linking hydronephrosis to polycythemia involves intrarenal hypoxia surrounding the peritubular interstitial EPO-producing cells, leading to increased erythropoiesis in response to local hypoxic conditions." (PMID 39767963, 2024). "The two factors that appeared to predict the detection of a reportable variant were low EPO (for PV and EPOR mutation) and a positive family history (for familial erythrocytosis)." (PMID 39335122, 2024). "Possible explanations for secondary polycythemia include tumor paraneoplastic production of erythropoietin, hypoxia‐driven response to tumor invasion, and cardiac dysfunction itself." (PMID 39713744, 2024). "SLC30A10 deficiency results in impaired gastrointestinal manganese excretion, leading to manganese excess, neurologic deficits, liver cirrhosis, polycythemia, and erythropoietin excess." (PMID 38652538, 2024). "Serum erythropoietin (EPO) level helps distinguish primary and secondary polycythemia, but it should be aided by further testing such as the JAK-2 gene mutation test." (PMID 39421127, 2024). "Serum erythropoietin (sEPO) is an initial screening tool for distinguishing polycythemia vera (PV) from secondary erythrocytosis (SE), but defining ‘subnormal’ sEPO levels for PV diagnosis remains contentious, complicating its clinical utility." (PMID 39272689, 2024). "As far as we are aware, there are just a few case reports in the literature that describe primary polycythemia cases with elevated blood EPO levels." (PMID 39421127, 2024). "Polycythemia can result from myeloproliferative disorders, known as polycythemia-vera, or can be secondary to increased red blood cells regulated by erythropoietin." (PMID 39286683, 2024). "SLC30A10 deficiency impairs gastrointestinal Mn excretion, resulting in severe Mn excess as well as neurologic and liver dysfunction, polycythemia, and erythropoietin (EPO) excess." (PMID 38652538, 2024). "The alteration of the VHL tumor suppressor gene results in the stabilization of hypoxia-induced factor 1/2α, which then increases the biosynthesis of erythropoietin (EPO), and thus leads to polycythemia." (PMID 38610939, 2024). "It produces erythrocytosis due to a multifactorial process, including the stimulation of erythropoietin, and the suppression of hepcidin, ferritin, and estradiol, which increases hematopoietic telomerase." (PMID 39407952, 2024).
polycythemia (continued). "Polycythemia is attributed to EPO excess, but the basis of EPO excess in this disease has yet to be established." (PMID 38652538, 2024). "Our findings suggest that hydronephrosis can lead to polycythemia through mechanisms other than increased EPO production, highlighting the need for further investigation into the underlying pathophysiology of this rare association." (PMID 39767963, 2024). "We report a case of an adolescent with progressive hydronephrosis-induced polycythemia and low erythropoietin levels, along with a thorough literature review." (PMID 39767963, 2024). "Although a role for HIFs in EPO excess and polycythemia in SLC30A10 deficiency has yet to be explored, several studies have shown links between Mn, EPO, and HIFs." (PMID 38652538, 2024). "There have also been case series describing PNETs secreting renin and erythropoietin, resulting in hypertension and polycythemia, respectively." (PMID 37046665, 2023). "Herein, we present a case of polycythemia with an elevated erythropoietin level in a patient with a urinary stone and unilateral hydronephrosis." (PMID 36890599, 2023). "TEMPI syndrome (TEMPI) compounds telangiectasias and polycythemia with elevated erythropoietin levels, monoclonal gammopathy, perirenal fluid collections, and intrapulmonary shunt." (PMID 39355028, 2023). "The administration of gliflozins also triggers erythropoietin (EPO) production, with the consequent induction of reticulocytosis and erythrocytosis." (PMID 37510986, 2023). "In a routine practice, decreased values of serum erythropoietin EPO points to the primitive character of erythrocytosis, suggesting the role of driver JAK2 mutations in the occurrence of erythrocytosis." (PMID 37239426, 2023). "In mouse, liver-specific deletion of VHL results in HIF-mediated hepcidin repression and EPO induction, leading to excessive (polycythemia) microcytic and hypochromic erythropoiesis." (PMID 37264878, 2023). "Although the EPO level is elevated in secondary polycythemia, it is mostly decreased in polycythemia vera due to negative feedback." (PMID 36890599, 2023). "This case was diagnosed as erythropoietin elevation due to unilateral hydronephrosis with a urinary stone, resulting in polycythemia." (PMID 36890599, 2023). "Herein, we present the first report of polycythemia with an elevated EPO level in a patient with a urinary stone and unilateral hydronephrosis." (PMID 36890599, 2023). "To evaluate the atherogenic role of VFEpoR RBCs in a model that mimics human polycythemia, we injected the same low-dose EPO into hyperlipidemic littermate EpoR-Cre control and VFEpoR mice that were fed the WD for 12 weeks." (PMID 35587375, 2022). "The most frequently identified causes of SE in our patients were IE in 56 (41.18%), chronic hypoxic states in 44 (32.4%), iatrogenic erythrocytosis (IaE) in 15 (11%), and autonomous EPO production in 10 (7.35%)." (PMID 35304527, 2022). "in 2011, the acronym was to describe the shared five clinical features (telangiectasias, elevated erythropoietin level and erythrocytosis, monoclonal gammopathy, perinephric fluid collections, and intrapulmonary shunting) presented in six patients." (PMID 35663307, 2022). "For instance, the typical manifestations of TEMPI syndrome include the pentad of telangiectasias, elevated erythropoietin and erythrocytosis, monoclonal gammopathy, perinephric fluid collections, and intrapulmonary shunting." (PMID 36358666, 2022). "Previous study illustrated therapeutic potential of blocking EPO/EPOR/JAK/STAT signaling in HCC patients with polycythemia." (PMID 35837663, 2022). "Complete blood counts 1 year later showed polycythemia according to the local age adjusted reference values (Hb 14.4 g/dL, elevated Hct) as well as thrombocytosis (1000 × 109/L), undetectable EPO levels, and elevated LDH (613 U/L)." (PMID 35819517, 2022).
polycythemia (continued). "Among these clinical manifestations, the incidence of polycythemia is relatively high, and some studies believe that MA can lead to polycythemia in patients by producing erythropoietin and some cytokines." (PMID 35463907, 2022). "A similar dysregulation of the IRP-1/HIF-2α pathway, which links erythropoiesis and iron availability, leads to unabated expression of the HIF-2α-target gene erythropoietin (EPO) and polycythemia in rare patients with mutations in IRP1 and IRP1-knockout mice." (PMID 35628152, 2022). "The phenotypes induced by low-dose EPO in hyperlipidemic VFEpoR mice resembled those seen in human polycythemia, with increased RBC counts, hematocrit, RDW, and splenomegaly." (PMID 35587375, 2022). "Essential for diagnosis is to recognize the five clinical findings: telangiectasias, erythrocytosis and elevated serum erythropoietin, monoclonal gammopathy, perinephric fluid collection, and intrapulmonary shunting." (PMID 36467823, 2022). "This is the case with TEMPI syndrome (Telangiectasias, elevated erythropoietin level and Erythrocytosis, Monoclonal gammopathy, Perinephric fluid collections, and Intrapulmonary shunting)." (PMID 36358666, 2022). "The typical manifestations of TEMPI syndrome include the pentad of telangiectasias, elevated erythropoietin and erythrocytosis, monoclonal gammopathy, perinephric fluid collections, and intrapulmonary shunting." (PMID 35663307, 2022). "Telangiectasias, elevated erythropoietin and erythrocytosis, and monoclonal gammopathy were listed as the major criteria." (PMID 35663307, 2022). "Based on the diagnostic criteria proposed by Sykes and colleagues, diagnosis of TEMPI syndrome depended highly on clinical manifestations with telangiectasias, elevated erythropoietin and erythrocytosis, and monoclonal gammopathy as the major criteria." (PMID 35663307, 2022). "Generally, erythrocytosis-associated mutations in JAK2 are often associated with low EPO, whereas those in EPAS1 are often associated with increased EPO." (PMID 34946900, 2021). "Because of polycythemia, a possible side effect of high-dose EPO in sepsis, a low dose of EPO was also tested here." (PMID 34831360, 2021). "Fourteen percent of our patients had increased serum EPO which distinguishes secondary from primary erythrocytosis." (PMID 34013406, 2021). "Rankin and colleagues showed that specific deletion of VHL in osteoprogenitors in mice (OSX:cre-VHLf/f) presented elevated EPO expression in bone, which was also accompanied by polycythemia." (PMID 33143240, 2020). "SP is associated with cardiopulmonary disorders, chronic obstructive pulmonary disease, sleep apnea syndrome, smoker polycythemia, renal polycythemia of EPO-producing tumors, polycystic kidney disease, altitude polycythemia, and large fibroids." (PMID 32341381, 2020). "The polycythemia mouse model with JAK2 V617F mutation in hematopoietic cells gives rise to constitutively active EPOR, low EPO concentrations in the serum, low trabecular bone volume, and reduced osteoblast number." (PMID 33330462, 2020). "At diagnosis of erythrocytosis, EPO serum levels were two times the upper limit of normal (ULN) and progressively reached nearly four times ULN (82 mU/ml) over time." (PMID 32546701, 2020). "At present, tumor burden is stable, polycythemia has resolved although erythropoietin levels are mildly elevated, and the patient is asymptomatic." (PMID 31185588, 2019). "Hypoxia can stimulate erythropoietin (EPO) synthesis and release that is the main mechanism of the occurrence of high-altitude polycythemia." (PMID 30984423, 2019). "In genetically modified mice, targeted deletion of VHL in osteoblasts over-stabilizes the hypoxic response and gives rise to high EPO production in osteoblasts that leads to severe polycythemia." (PMID 32038269, 2019). "Germline VHL pathogenic mutations are also reported in patients with PHEO and polycythemia, causing by stabilized HIF-2α and elevated production of erythropoietin." (PMID 30925729, 2019).
polycythemia (continued). "The Chuvash population of the Russian Federation is associated with a high prevalence of polycythemia due to VHL gene mutation that reduces oxygen dependent HIF-2α degradation and increases EPO production." (PMID 32038269, 2019). "The possible side effects of EPO in humans include hypertension, coagulation disorders, and polycythemia." (PMID 31821342, 2019). "The clinical course of a patient with IE is described manifesting as a persistent erythrocytosis with a low serum erythropoietin level, mild eosinophilia, and with evidence of a thrombotic event." (PMID 29682367, 2018). "On the other hand, secondary polycythemia occurs due to high levels of circulating factors, usually EPO, which is a principal regulator of erythropoiesis." (PMID 29534684, 2018). "Several studies have reported cases of complete response to HD-IL2 and IFN-α immunotherapy in patients with mRCC in conditions of erythrocytosis and elevated erythropoietin." (PMID 29853890, 2018). "Stringent VEGF inhibition increases hepatocyte erythropoiesis and polycythemia, which is mediated by increased erythropoietin production due to HIF2 activation." (PMID 29311569, 2018). "He presented with the two major criteria (i.e., erythrocytosis and the JAK2V617F mutation) and one minor criterion (i.e., low or lower end of normal serum erythropoietin levels)." (PMID 30564468, 2018). "On the other hand, embryonic or postnatal ablation of tubular VEGF results in the formation of a smaller kidney with a striking reduction in the peritubular capillary density and polycythemia due to increased renal erythropoietin production." (PMID 27454431, 2016). "MA has been reported to have the highest level of polycythemia among all kidney tumors, which is probably related to the production of erythropoietin and multiple cytokines by MA." (PMID 27784295, 2016). "A decrease in oxygen delivery (i.e., residence at high altitudes) stimulates EPO production, while increased oxygen delivery (i.e., erythrocytosis) decreases EPO production." (PMID 26768152, 2016). "In our patient who smoked and was diagnosed with sleep apnea, low erythropoietin levels prevented us from trivializing her polycythemia and misdiagnosing a hypoxemia-related erythrocytosis." (PMID 26187587, 2015). "This increase in erythropoietin is thought to be one of the mechanisms of testosterone-induced erythrocytosis." (PMID 26137331, 2015). "Polycythemia is one of the paraneoplastic syndromes associated with renal cell carcinoma (RCC), which has been associated with erythropoietin (EPO) production from renal carcinoma cells." (PMID 25295086, 2014). "In conclusion, EPO production from RCC and renal cysts in ADPKD appeared to cause polycythemia in the HD patient." (PMID 25295086, 2014). "Due to the remission of polycythemia following the nephrectomy, EPO production from the resected kidney appeared to have been the cause of the polycythemia." (PMID 25295086, 2014). "The main therapeutic use is the treatment of anemia resulting from chronic kidney disease, while the measurement of serum levels of EPO is important in differentiating primary polycythemia from secondary polycythemia." (PMID 24865486, 2014). "We propose the investigation of disturbances of oxygen sensing and erythropoietin signaling pathways in cases of idiopathic erythrocytosis with positive family history of erythrocytosis/thromboembolism." (PMID 24363938, 2013). "Our results also show that total flavonoids decreased serum erythropoietin level in high-altitude polycythemia rats." (PMID 23023684, 2012). "With some strains of SFFV, erythropoietin (Epo)-independent differentiation of erythroid cells also occurs, resulting in polycythemia." (PMID 21994618, 2010). "In contrast, SPL only blunts hematocrit elevation in secondary, erythropoietin-induced polycythemia." (PMID 19789710, 2009).
polycythemia (continued). "We first optimized a dosing regimen of recombinant human erythropoietin (AranespTM) that induces polycythemia in mice, and closely recapitulates the pathologic hallmarks of human PV." (PMID 19789710, 2009). "Polycythemia is usually attributed to pathologic erythropoietin production by the tumor or by the adjacent normal parenchyma in response to hypoxia induced by tumor growth." (PMID 16995951, 2006). "The patient demonstrated significant hyperandrogenemia and polycythemia driven by erythropoietin." (PMID 41788783, 2026). "Primary erythrocytosis, as seen in polycythemia vera, presents with suppressed EPO due to intrinsic hematopoietic stem cell abnormalities, while secondary erythrocytosis is marked by elevated or inappropriately normal EPO in response to hypoxia or ectopic production." (PMID 41012526, 2025). "However, cases of cancer-related hypoglycemia in patients with ACC have been described or hyperrenin hyperaldosteronism and erythropoietin-related polycythemia." (PMID 40007812, 2025). "However, EPO testing is recommended for the workup of undifferentiated erythrocytosis, and low EPO remains a minor criterion in the WHO 2018 criteria for the diagnosis of polycythemia vera." (PMID 40806795, 2025). "Neonatal polycythemia develops due to higher glucose uptake and high levels of erythropoietin." (PMID 41007128, 2025). "The findings suggest that radiation therapy normalizes serum EPO levels and improves polycythemia." (PMID 40502212, 2025). "Chuvash polycythemia has characteristics of both primary and secondary polycythemic diseases, as the erythroid progenitors of these patients show EPO hypersensitivity and EPO levels are elevated in Chuvash polycythemia." (PMID 40130200, 2025). "While EPO demonstrates clear metabolic benefits in preclinical models, its erythropoietic activity poses clinical limitations—particularly in individuals with obesity-related comorbidities—due to risks such as polycythemia and thrombosis." (PMID 40697664, 2025). "For example, noncoding erythropoietin (EPO) promoter variants recently linked to hereditary erythrocytosis suggest that population-enriched regulatory mutations can elevate red cell production independent of serum EPO levels detectable by standard assays." (PMID 40703258, 2025). "True polycythemia can further be subdivided into primary and secondary polycythemia, depending on whether the patient has a low or elevated erythropoietin (EPO) level, respectively." (PMID 40248540, 2025). "Notably, WBRT appeared to contribute to the normalization of serum EPO levels and resolution of polycythemia." (PMID 40502212, 2025). "In polycythemia patients, the spleen becomes congested with RBCs, leading to structural disorganization and functional impairment, similar to the microstructural disorder and splenic corpuscular atrophy observed in our EPO-treated mice." (PMID 40191193, 2025). "Serum EPO level is usually the next step in evaluating patients with absolute polycythemia." (PMID 39421127, 2024). "Our patient has an elevated EPO, which is usually seen in secondary polycythemias." (PMID 39421127, 2024). "Generally, high affinity variants become fully saturated with oxygen in the lung, but at a tissue capillary pO2 of 35–45 mm Hg, they deliver less oxygen than normal Hb A. This results in mild tissue hypoxia which stimulates increased erythropoietin production and subsequent polycythemia." (PMID 39713528, 2024). "Acute episodes of hypoxia can stimulate the production of erythropoietin, which induces erythrocytosis and may contribute to an increase in RDW in COPD patients." (PMID 39643902, 2024). "Other genetic mutations, such as SLC30A10, have also been associated with polycythemia without elevated EPO levels." (PMID 39767963, 2024). "It is characterized by neurologic and liver dysfunction, polycythemia, and EPO excess." (PMID 38652538, 2024).